SLC4A4 (solute carrier family 4 member 4)
Description:
Electrogenic sodium/bicarbonate cotransporter with a Na(+):HCO3(-) stoichiometry varying from 1:2 to 1:3. May regulate bicarbonate influx/efflux at the basolateral membrane of cells and regulate intracellular pH.
Synonyms: NBC1; NBCE1; HNBC1; NBC2; pNBC; hhNMC; kNBC1; KNBC; NBCe1-A; PRTAO; SLC4A5
Tractability: Antibody: UniProt places it where antibodies can reach, with high confidence; its Gene Ontology location is reachable by antibodies, with high confidence; UniProt predicts a signal peptide or a membrane-spanning region. PROTAC: ubiquitination databases record sites on it; its protein half-life has been measured.
Gene: Protein-coding gene on chromosome 4 (71,062,667 to 71,572,087, forward strand). Ensembl gene ENSG00000080493.
Subcellular location: Basolateral cell membrane; Cell membrane
Subcellular location (Human Protein Atlas): Plasma membrane; Cytosol
Pathways (Reactome):
Developmental Biology: Developmental Lineage of Pancreatic Ductal Cells
Disease: Defective SLC4A4 causes renal tubular acidosis, proximal, with ocular abnormalities and mental retardation (pRTA-OA)
Transport of small molecules: Bicarbonate transporters
Gene Ontology:
Molecular function: identical protein binding; protein binding; sodium:bicarbonate symporter activity; symporter activity; monoatomic anion transmembrane transporter activity; solute:inorganic anion antiporter activity
Biological process: bicarbonate transport; positive regulation of glycolytic process; regulation of intracellular pH; regulation of membrane potential; sodium ion export across plasma membrane; sodium ion transmembrane transport; sodium ion transport; transmembrane transport; transport across blood-brain barrier; monoatomic anion transmembrane transport; monoatomic anion transport
Cellular component: basolateral plasma membrane; cell surface; extracellular exosome; membrane; plasma membrane
Genetic constraint (gnomAD): Loss-of-function variants: 20 observed, 88.25 expected, observed/expected ratio (o/e) 0.23, 90% interval 0.16 to 0.33. The upper end of that interval is the gene's LOEUF score, 0.33, which puts it in group 1 of 6, group 1 being the genes least tolerant of losing a copy. Missense variants: 781 observed, 1,196.3 expected, observed/expected ratio (o/e) 0.65, 90% interval 0.62 to 0.69. Synonymous variants: 381 observed, 430.64 expected, observed/expected ratio (o/e) 0.88, 90% interval 0.81 to 0.96.
Homologues: Orthologues: dog SLC4A4 (97% identical), mouse Slc4a4 (97% identical), pig SLC4A4 (97% identical), rat Slc4a4 (97% identical), chimpanzee SLC4A4 (96% identical), macaque SLC4A4 (96% identical), rabbit SLC4A4 (93% identical), guinea pig SLC4A4 (89% identical), tropical clawed frog slc4a4 (86% identical), zebrafish slc4a4a (84% identical), zebrafish slc4a4b (78% identical), Drosophila melanogaster Ndae1 (46% identical), and 3 more. Paralogues in human: SLC4A5 (62% identical), SLC4A7 (54% identical), SLC4A10 (53% identical), SLC4A8 (53% identical), SLC4A9 (47% identical), SLC4A2 (37% identical), SLC4A3 (36% identical), SLC4A1 (32% identical), SLC4A11 (21% identical).
Diseases named in the same sentence as SLC4A4 in open-access papers:
SLC4A4 is named in the same sentence as 111 diseases in open-access papers, as found by Europe PMC text mining. Sharing a sentence is not in itself a finding about the gene and the disease. The quoted sentences say what the papers report.
proximal renal tubular acidosis (25 papers, 2007 to 2026). Proximal renal tubular acidosis (pRTA) is a tubular kidney disease characterized by impaired ability of the proximal tubule to reabsorb bicarbonate from the glomerular filtrate leading to hyperchloremic metabolic acidosis. "Proximal renal tubular acidosis (pRTA) with ocular abnormalities is an autosomal recessive disease caused by variants in the Solute Carrier Family 4 Member 4 (SLC4A4) gene." (PMID 36061388, 2022). "Homozygous point mutations in electrogenic sodium bicarbonate co-transporter 1 (NBC1), in humans encoded by the SLC4A4 gene, cause proximal renal tubular acidosis (pRTA), glaucoma, and cataracts, usually accompanied by mental retardation." (PMID 33919241, 2021). "Homozygous mutations in SLC4A4 encoding the sodium bicarbonate cotransporter NBCe1 are usually associated with proximal renal tubular acidosis, with ocular abnormalities (RTA, OMIM #604278), which can also feature mental retardation and short stature." (PMID 33126486, 2020). "Congenital NBCe1A deficiency with the SLC4A4 mutation causes severe proximal renal tubular acidosis, which often comprises extrarenal symptoms, such as intellectual disability and developmental delay, glaucoma, cataract and band keratopathy." (PMID 29914390, 2018). "This is the first report of congenital proximal renal tubular acidosis carrying compound heterozygous SLC4A4 mutations in exon–intron boundary regions." (PMID 29914390, 2018). "Mutations in the sodium bicarbonate cotransporter NBCe1 (SLC4A4) cause proximal renal tubular acidosis (pRTA)." (PMID 29449648, 2018). "Meanwhile, mutations in SLC4A4, a traditional sodium bicarbonate cotransporters, cause proximal renal tubular acidosis as well as ocular anomalies, such as glaucoma, cataracts, and band keratopathy in human." (PMID 28934248, 2017). "Moreover, five members (III:6, III:9, IV:4, IV:7, and V:3) presented with a heterozygous variant of SLC4A4, which is responsible for isolated proximal renal tubular acidosis, an autosomal recessive disease." (PMID 35087831, 2021). "Hemiplegic migraine and MA/MO also occur as a comorbidity in proximal renal tubular acidosis (pRTA) patients carrying certain homozygous mutations in the SLC4A4 gene (encoding the Na+-HCO3− cotransporter NBCe1), in which mutations in the other known FHM-related genes were ruled out." (PMID 27445835, 2016). "Autosomal recessive proximal renal tubular acidosis (AR-pRTA) with ocular abnormalities is a rare syndrome caused by variants in the SLC4A4 gene, which encodes Na/HCO3 cotransporter (NBCe1)." (PMID 39869206, 2025). "Congenital proximal renal tubular acidosis (pRTA) is a rare systemic disease caused by mutations in the SLC4A4 gene that encodes the electrogenic sodium bicarbonate cotransporter, NBCe1." (PMID 39273556, 2024). "In relation to SLC4A4, variants of this gene may cause impairment of bicarbonate reabsorption in the proximal renal tubules, causing a decrease in the threshold of renal bicarbonate and resulting in proximal renal tubular acidosis." (PMID 34439758, 2021). "In addition to the hypomineralized enamel phenotype, patients with mutations in SLC4A4 have corneal opacities (band keratopathy), cataracts, glaucoma, severe proximal renal tubular acidosis, calcification of the basal ganglia, elevated serum amylase and lipase, and mental retardation." (PMID 24828138, 2014). "Mutations in SLC4A4 have been reported in pedigrees with proximal renal tubular acidosis (pRTA) with HM and migraine, but this gene was not considered in this study as none of the patients in our series showed renal abnormalities." (PMID 24498617, 2013). "Mutations in human SLC4A4, another HCO3− transporter (NBC1, Na+/HCO3− co-transporter), have been associated with short stature, poor dentition, proximal renal tubular acidosis, and bilateral cataracts with corneal opacity and late blindness onset in humans." (PMID 17786210, 2007).
proximal renal tubular acidosis (continued). "Recessive loss-of-function variants in SLC4A4 cause proximal renal tubular acidosis, no brain edema." (PMID 41841191, 2026). "SLC4A4 - In two patients with proximal renal tubular acidosis and a homozygous frameshift mutation S982NfsX4 in SLC4A4, which encodes for a sodium bicarbonate cotransporter NBCe1, hemiplegic migraine was reported, while some heterozygous carriers reported common forms of migraine." (PMID 32503413, 2020). "Slc4a4-null mice are a model of proximal renal tubular acidosis (pRTA)." (PMID 24828138, 2014).
breast carcinoma (17 papers, 2014 to 2024). "These analyses revealed that lower SLC4A4 significantly associated with poorer progression of patients with malignancies, including breast cancer, lung cancer, gastric cancer, and ovarian cancer." (PMID 32284764, 2020). "SLC4A4 associated with proliferation and migration in colon and breast cancer." (PMID 33648461, 2021). "Due to the decrease of SLC4A4 mRNA expression in multiple malignancies, including breast cancer, lung cancer, gastric cancer, and ovarian cancer, we further assessed the correlation between SLC4A4 mRNA expression and survival of patients, including OS, RFS, PPS, DMPS, FP or PFS." (PMID 32284764, 2020). "Survival analysis based on SLC4A4 expression in multiple malignancies (including breast cancer, lung cancer, gastric cancer, and ovarian cancer) demonstrated that lower SLC4A4 expression significantly correlated with poorer progression (including OS, RFS, PPS, DMPS, FP or PFS) of patients." (PMID 32284764, 2020). "SLC4A4 has been reported to promote colon and breast cancer growth and migration." (PMID 30668544, 2019). "The deficiency of SLC4A4 (NBCe1), an electrogenic Na+/HCO3– co-transporter, was influenced by cell migration by interfering with the intracellular pH regulatory mechanism in MDA-MB 231 breast cancer cells." (PMID 31480869, 2019). "Another gene, SLC4A4, was found to be significantly correlated with shorter survival of CRC patients and a marker of poorer progression for patients with breast cancer, lung cancer, gastric cancer, and ovarian cancer." (PMID 35336739, 2022). "However, some general trends are observed across all breast cancer subtypes: SLC4A1, SLC4A4, SLC26A3, and SLC26A4 seem to be consistently down-regulated, while SLC4A5 is up-regulated, in all breast cancer subtypes compared to normal breast tissue." (PMID 24795638, 2014).
glaucoma (11 papers, 2009 to 2021). Increased pressure in the eyeball due to obstruction of the outflow of aqueous humor. "Less is known about Slc4a4 in SGNs, however, mutations in the human SLC4A4 gene have been associated with neurosensory disorders including glaucoma and hereditary sensory neuropathy type I." (PMID 32523514, 2020). "This variant NM_003759.3:c.*206G>A is in the 3′UTR of SLC4A4, a gene known to be mutated in a rare autosomal syndromic form of intellectual disability that is characterized by severe renal tubular acidosis and ocular involvement, the latter being in the form of glaucoma and keratopathy." (PMID 28754144, 2017). "Loss-of-function mutations in the gene that codifies the NBC-1, the SLC4A4 gene, were first identified in two Japanese subjects with proximal RTA associated with cataracts, glaucoma and band keratopathy." (PMID 19721811, 2009). "We performed direct nucleotide sequencing analysis of exons and exon–intron boundary regions of the SLC4A4 in a patient presenting with severe renal proximal tubule acidosis, glaucoma and intellectual disability and her parents without these signs." (PMID 29914390, 2018).
colon carcinoma (8 papers, 2020 to 2023). "The acid microenvironment caused by bicarbonate reduction also increased the expression of SLC4A4 in colon cancer cell lines." (PMID 37189084, 2023). "Moreover, in Ls174T (colon cancer) cells, hypoxic induction of Slc4a4 is regulated by HIF-1α and sequences for HIF-1α binding sites were found in the Slc4a4 promoter." (PMID 36012235, 2022).
Hypertension (7 papers, 2012 to 2022). The presence of chronic increased pressure in the systemic arterial system. "Defects in three of these genes, Slc6a19, Slc4a4, and Lrp2 have been linked to hypertension." (PMID 27462279, 2016). "Among them, IGF1, SLC4A4, and WWOX were previously implicated as hypertension candidate genes in humans and mice and are primarily associated with obesity, glucose metabolism, and ion homeostasis, which are well-known mechanisms of blood pressure regulation." (PMID 22479346, 2012). "Four hypertension susceptibility genes, IGF1, SLC4A4, WWOX, and SFMBT1, were found by a statistical permutation procedure, confirmed by gene expression analysis, and further replicated using data from the HKHS." (PMID 22479346, 2012).
colorectal cancer (6 papers, 2020 to 2025). A primary or metastatic malignant neoplasm that affects the colon or rectum. "A noteworthy association has been observed between SLC4A4 expression and reduced survival in patients with colorectal cancer (CRC), as well as worse prognosis in patients with gastric, ovarian, lung, and breast cancer." (PMID 39852182, 2025). "PCR showed that SLC4A4 was significantly down-regulated in colorectal cancer cell lines Caco-2, HCT116 and HT29 compared with normal control NCM460 cell lines." (PMID 37152025, 2023). "The results showed that SLC4A4 was significantly down-regulated in colorectal cancer cell lines Caco-2, HCT116 and HT29 compared with normal control NCM460 cell lines (***P<0.001)." (PMID 37152025, 2023). "Prognostic predictive model according to age, tumor stage, and SLC4A4 expression showed effective performance in the prediction of overall survival among colorectal cancer patients at 1, 3, and 5 year." (PMID 35305629, 2022). "In summary, the molecular mechanism of SLC4A4 in the development of colorectal cancer is very important and requires further research to elucidate." (PMID 32662230, 2020). "Targeting SLC4A4 in colorectal cancer (CRC) therapy could play a crucial role in regulating tumor acidity and modulating immune responses within the tumor microenvironment (TME)." (PMID 39852182, 2025). "Immunohistochemistry also showed low expression of SLC4A4 in colorectal cancer." (PMID 37152025, 2023). "PCR assay was used to investigate the expression of SLC4A4 in colorectal cancer cell lines." (PMID 37152025, 2023). "This might appear in contradiction with in vitro evidence performed in breast, prostate and colorectal cancer cells where Slc4a4 silencing negatively affects cancer cell proliferation." (PMID 36522548, 2022). "SLC4A4, as a tumor suppressor gene, is significantly downregulated and positively correlated with microsatellite instability, thus it may be combined with microsatellite instability to guide colorectal cancer treatment." (PMID 37152025, 2023). "Here, for the first time, we identified a significant positive correlation between SLC4A4 and MSI in colorectal cancer." (PMID 37152025, 2023). "The combination of SLC4A4 and MSI can predict the prognosis and outcomes of colorectal cancer patients and guide clinical medication, providing innovative recommendations for personalized medicine." (PMID 37152025, 2023).
migraine (6 papers, 2013 to 2024). "In this study, we further examined the channelopathic nature of a migraine through the analysis of common genetic variants in three selected ion channel or transporter genes: SLC4A4, SLC1A3, and CHRNA4." (PMID 38927733, 2024). "Given the notion that NBCe1 dysfunction affects pH and the functioning of astrocytes, the possible involvement of SLC4A4 in migraine pathophysiology deserves further investigation." (PMID 32503413, 2020). "In recent years several genes have been put forward as possible hemiplegic migraine genes (i.e. PRRT2, SLC1A3 and SLC4A4), but evaluation of available data should cast doubt on such claims." (PMID 32503413, 2020).
clear cell renal cell carcinoma (5 papers, 2019 to 2022). "However, miR-223-3p was found to promote cell proliferation and metastasis in clear cell renal cell carcinoma by downregulating SLC4A4, further supporting the association of Slc4a4 and miR-223-3p." (PMID 32727087, 2020). "SLC4A4 was found to be significantly downregulated in the clear cell renal cell carcinoma tissues, low expression of which was corelated with poor prognosis." (PMID 31612869, 2019).
Obesity (5 papers, 2012 to 2025). Accumulation of substantial excess body fat. "The mEC1 population showed an obesity-induced downregulation of transporters of major ions (Slc34a1, Slc4a4, Slc22a8, Slc13a1, Slc22a18 and Slc5a12), neutral amino acids (Slc6a19) and glucose (Slc5a2)." (PMID 36400935, 2022). "Some studies have shown that SLC4A4 may be involved in the pathogenesis of obesity and also participate in immune infiltration, and the methylation of the solute carrier protein (SLC) gene has been closely related to BMI and waist circumference." (PMID 36313453, 2022). "In another integrative methylome–transcriptome analysis, seven key genes were identified—CCRL2, GPT, LGALS12, PC, SLC27A2, SLC4A4, and TTC36—that were hypermethylated in obesity and concurrently showed reduced expression." (PMID 41303351, 2025). "In summary, we successfully identified seven key genes, namely, CCRL2, GPT, LGALS12, PC, SLC27A2, SLC4A4, and TTC36, which are involved in obesity occurrence and development likely through the immune microenvironment." (PMID 36313453, 2022). "In this study, by analyzing three GEO datasets and verifying in 24 patients, we identified that CCRL2, GPT, LGALS12, PC, SLC27A2, SLC4A4, and TTC36 might be the key genes that play an important role in obesity pathogenesis." (PMID 36313453, 2022). "In this study, not only SLC4A4 but also SLC27A2 were both significantly downregulated in obese patients, which to a certain extent supports previous studies and suggests that these two genes might be key genes requiring more attention in the future exploration of the obesity mechanism." (PMID 36313453, 2022).
prostate carcinoma (5 papers, 2013 to 2025). A carcinoma that arises from epithelial cells of the prostate gland. "A previous study showed that SLC4A4 is increasingly expressed in prostate cancer tissues and cell lines." (PMID 36618366, 2022). "SLC4A4 promotes prostate cancer progression through the Akt-mediated signaling pathway." (PMID 36618366, 2022).
renal tubular acidosis (5 papers, 2017 to 2023). A group of genetic disorders of the kidney tubules characterized by the accumulation of metabolically produced acids with elevated plasma chloride, hyperchloremic metabolic acidosis. "For example, the gene solute carrier family 4 member 4 (SLC4A4) encodes a sodium bicarbonate cotransporter, and the gene has been associated with renal tubular acidosis." (PMID 36830584, 2023). "A second variant (p.(Gly50Ala)) in heterozygosis of maternal origin is located in the SLC4A4 gene (OMIM: #603345), which is associated with the phenotype of renal tubular acidosis with autosomal recessive ocular involvement (MIM: #604278)." (PMID 37895187, 2023).